EXO1 (exonuclease 1)
Diseases named in the same sentence as EXO1 in open-access papers (continued):
Sharing a sentence is not in itself a finding about the gene and the disease.
cancer (continued). "Dysfunction of EXO1 could impair DNA repair processes which can cause replication stress followed by genomic instability and development of cancer." (PMID 36606188, 2022). "EXO1 overexpression is associated with poor prognosis in several cancers." (PMID 35769911, 2022). "However, both Exo1DA/DA and Exo1–/– mice displayed similar mortality and cancer predisposition profiles." (PMID 35849338, 2022). "However, in genomic-wide association studies (GWAS), specific mutations in EXO1 have been identified as risk alleles for the development of multiple types of cancer." (PMID 30585186, 2018). "K589E (rs1047840) may replace risk of cancer as a potentially functional polymorphism in Exo1 gene by influencing the repair activity of that." (PMID 30774822, 2018). "Based on these data, we envision that cancers triggered by EXO1 mutations may be nearly as common as those initiated by MSH6 mutations." (PMID 29069084, 2017). "Thus, we aimed to obtain a thorough and current assessment of EXO1 polymorphisms and cancer susceptibility by performing a meta-analysis." (PMID 27387683, 2016). "In conclusion, our meta-analysis suggests that the rs1047840, rs9350, rs10802996, rs1635498, rs1776148, rs1776177, rs3754093 and rs851797 polymorphisms in EXO1 may be risk factors for cancer." (PMID 27387683, 2016). "Secondly, the effects of EXO1 polymorphisms on cancer susceptibility might be affected by several factors, such as age, sex, smoking status and matching criteria." (PMID 27387683, 2016). "However, further well-designed studies in large cohort of different ethnic origins and cancer types are needed before the application of Exo1 K589E polymorphism as cancer biomarker in clinical settings and early cancer detection." (PMID 24810280, 2014). "In conclusion, Exo1 K589E Lys allele may be used as a novel biomarker for cancer susceptibility, particularly in smokers." (PMID 24810280, 2014). "Main results of pooled ORs of the Exo1 K589E polymorphisms on cancer risk in the meta-analysis." (PMID 24810280, 2014). "The Exo1 exonuclease plays a major role in the repair of DSBs and mismatches, and mutations in Exo1 or deregulation of its function are associated with increased cancer susceptibility, telomere defects and ageing." (PMID 23939618, 2013). "Finally, our study revealed that EXO1 may be associated with the sensitivity to multiple anticancer drugs that inhibit proliferation or interfere with the cell cycle of cancer cells." (PMID 40433389, 2025). "In addition, several EXO1 polymorphisms have been associated with a high risk of prostate, ovarian, lung, oral, liver, colon and stomach cancer, whereas other variants have shown protective roles in tissues like liver and colon." (PMID 35883600, 2022). "Therefore, the variations in EXO1 have been linked to various types of cancers." (PMID 34950206, 2021). "That finding allowed the authors to propose that EXO1 mutations may predispose humans to cancer." (PMID 29069084, 2017). "Exonuclease 1 (EXO1) is a critical enzyme in homologous recombination (HR) and is implicated in cancer progression, with overexpression linked to poor prognosis in multiple tumor types." (PMID 41323735, 2025). "Here we define synthetic lethal interactions with exonuclease EXO1, which has revealed known and previously unappreciated genetic vulnerabilities that exist in many cancers." (PMID 41006228, 2025). "Given its dual role inDNA replication and DSB repair, EXO1 notonly is an attractive target for cancer cell-specific killing butalso has high potential for inducing synthetic lethality (SL) of cancercells." (PMID 40378357, 2025). "Analysis of data from TCGA database through the UALCAN webpage revealed that the promoter methylation level of EXO1 was significantly lower in tumor tissues compared to normal tissues in various cancers, including BRCA, UCEC, and THCA." (PMID 40433389, 2025).
cancer (continued). "Identifying hub genes such as TPX2, MKI67, and EXO1, which are involved in cell cycle regulation and DNA repair, further supports the cancer-specific relevance of our biomarkers." (PMID 40445003, 2025). "Our analysis revealed that EXO1 expression was broadly correlated with immune regulatory molecules across female-related cancers." (PMID 40433389, 2025). "We conducted a comprehensive evaluation of the potential roles of EXO1 in different female-related cancers using RNA-seq data from TCGA database." (PMID 40433389, 2025). "As its exonucleaseactivity is essential for homologous recombination (HR) and replicationfork processing, EXO1 has emerged as a compelling therapeutic target,especially in cancers marked by heightened DNA damage and replicationstress." (PMID 40378357, 2025). "Results from TIMER 2.0 database demonstrated that among various types of cancers, UCEC had the highest mutation frequency for EXO1, with 28/531 cases showing mutations." (PMID 40433389, 2025). "In specific cancer subtypes like the basal-like subtype of BRCA, high EXO1 expression is associated with a better prognosis." (PMID 40433389, 2025). "The results consistently showed that the infiltration levels of Th2 cells were higher in the high EXO1 expression group across all six cancer types." (PMID 40433389, 2025). "This analysis underscores EXO1’s central role in mismatch repair, establishing it as a key gene for studying DNA repair-related cancers." (PMID 39777332, 2024). "Because EXO1 functions in a variety of DNA repair pathways, the relationship between this gene and cancer has previously been investigated." (PMID 39046429, 2024). "We conducted an investigation into the variations in EXO1 protein expression between cancer-adjacent tissues and LUAD tissues by evaluating the expression levels of EXO1 and its associated proteins through immunohistochemistry." (PMID 39777332, 2024). "The use of EXO1 as a biomarker has been demonstrated to improve the accuracy and reliability of cancer detection." (PMID 39777332, 2024). "Due to their dual roles in DNA replication and DSB repair, DNA2 and EXO1 are not only two exceptional targets for cancer cell-specific killing, but also two outstanding targets for inducing synthetic lethality of cancer cells." (PMID 38714348, 2024). "It was reported that EXO1 works as a guardian of our genome to reduce cancer progression by inducing DNA damage checkpoints and DNA damage repair." (PMID 36971680, 2023). "In this study, we demonstrated that EXO1 was significantly overexpressed in 19 out of the 33 human cancer tissues." (PMID 35769911, 2022). "By analysing the TCGA database, we found that CCNB1, CDC25C, CENPM, and EXO1 were highly expressed in almost all of the 33 cancers, and we also noticed significant high expression in LUAD." (PMID 35646074, 2022). "Overexpression of EXO1 occurs in prostate, breast, ovarian (cell lines), lung, liver, bladder and melanoma cancer patients." (PMID 35883600, 2022). "Exonuclease 1 (EXO1) is associated with increased levels of genomic instability in the telomere region, and this widespread genomic instability can promote cancer progression." (PMID 34408776, 2021). "EXO1 genes which are related to mismatch repairing were recognized as the new cancer driver genes in a recent study, which are closely related to m6A RNA methylation-related genes." (PMID 33540684, 2021). "The link between EXO1 and cancer is still under continuous research and much progress has been made." (PMID 32626539, 2020). "EXO1 has also been reported to be overexpressed in several other cancers as described in the introduction 15, 16, 51-53." (PMID 32626539, 2020).
cancer (continued). "For example, TPX2, a microtubule-binding protein, is a hub gene in all 8 cancer types, while EXO1 and BUB1 are hub genes in 5 cancer types." (PMID 31179925, 2019). "We will herein examine the putative wider roles of EXO1 as a guardian of our genome and investigate its possible role in cancer progression and initiation." (PMID 30585186, 2018). "In this review, we summarize the involvement of EXO1 in the replication, DNA repair pathways, cell cycle checkpoints, and the link between EXO1 and cancer." (PMID 30585186, 2018). "EXO1 activity contributes to several DNA repair processes; however, it is not clear if the absence or malfunction of EXO1 can contribute to cancer development." (PMID 30585186, 2018). "Nevertheless, the overexpression of EXO1 has also been reported in several other cancers, which in part is related to increased DNA repair activity." (PMID 30585186, 2018). "While the relevance of FH, EXO1, MAP1LC3C and PLD5 functions to the development of cancer is plausible, that of the associated RGS7 is intriguing and deserves comments." (PMID 23555580, 2013). "Since these alkylating agents also would elevate the genomic instability in cancer cells upon exposure, these results also indicate that EXO1 expression is indicative of elevated genomic instability in cancer cells." (PMID 24147022, 2013). "Hence, the EXO1 protein likely plays a significant role in cancer chemoresistance and holds promise as a therapeutic target for enhancing chemosensitivity in drug-resistant patients." (PMID 40433389, 2025). "EXO1 performs multiple roles in DNA replication and DNA damage repair (DDR), but its role in DDR-deficient cancers remains unclear." (PMID 41006228, 2025). "Lastly, we investigated the correlation between EXO1 expression and drug sensitivity in cancers." (PMID 40433389, 2025). "Given thatcancer cells require EXO1 to counteract the immensestress of abnormal DNA replication, smallmolecules targeting EXO1 exonuclease activity represent a major opportunityfor specifically killing cancer cells." (PMID 40378357, 2025). "Evidently, TYMS inhibitor Pemetrexed should not be used in any future EXO1 therapeutic combinations in FA-deficient cancers." (PMID 41006228, 2025). "Given that EXO1 plays a crucial role in regulating the cell cycle and DNA repair processes, it is expected to be upregulated in proliferating cells, particularly in cancer cells characterized by an active cell cycle and high proliferation rate." (PMID 40433389, 2025). "Altogether, our data argue for the development of EXO1 inhibitors, which would be differentiated from and combine effectively with existing therapies to expand the therapeutic options for treating DDR-deficient cancers." (PMID 41006228, 2025). "In this study, we testedif targeting EXO1 may exploit a specificvulnerability in cancer cells, assuming that normal cells are betterprotected by intact cell cycle checkpoints and redundant DNA repairprocesses." (PMID 40378357, 2025). "Our analysis also revealed cancer subtype-specific patterns, in BRCA and THCA, EXO1 showed positive associations with regulatory T cells (Tregs) and activated dendritic cells (aDC), whereas UCEC and OV exhibited inverse correlations with cytotoxic CD8+ T cells." (PMID 40433389, 2025). "However, Project Achilles19, available through the DepMap portal, which collates information on cancer dependencies, defines EXO1 as a ‘strongly selective’ gene, indicating that EXO1 is essential in a subset of cancers." (PMID 41006228, 2025). "To determine whether EXO1 is overexpressed in human cancers, we surveyedthe TCGA database for EXO1 expression levels." (PMID 40378357, 2025). "Moreover, we consistently observed higher infiltration levels of Th2 cells in the high EXO1 expression groups across all six cancer types." (PMID 40433389, 2025).
cancer (continued). "As these deficiencies in cancers are not currently associated with an effective therapeutic strategy, these findings bring EXO1 to the forefront of targets for their treatment." (PMID 41006228, 2025). "This is particularly relevant since alterations of EXO1 expression could enhance and uncover a neglected detrimental effect of SETX deficiency in cancer." (PMID 39120648, 2024). "Increased predisposition to cancer has been reported in patients carrying variants in EXO1 but not confirmed." (PMID 39595984, 2024). "Additionally, the wound healing assays provide compelling evidence that EXO1 facilitates cell migration, a critical process in cancer metastasis." (PMID 39777332, 2024). "Inhibition of EXO1 activity has emerged as a promising therapeutic strategy in cancer treatment." (PMID 39777332, 2024). "To assess whether our findings about Senataxin and EXO1 roles in cGAS positive MN production could influence the pathogenesis of human cancer, we studied the expression of these two proteins in different publicly available data sets in the TCGA repository." (PMID 39120648, 2024). "EXO1 inhibited the activity of cancer progression through PARP pathway." (PMID 36971680, 2023). "What’s more, the logFC of EXO1 is 3.9, ranking the highest in cancer progression genes." (PMID 36971680, 2023). "Therefore, a lower EXO1 expression will be beneficial to cancer patients in platinum salts treatment, which has been validated in ovarian cells." (PMID 36255267, 2022). "Furthermore, HCC patients with high AFP levels, low OS and DSS rates, and advanced cancer stages also showed higher EXO1 levels." (PMID 35769911, 2022). "The link between EXO1 and cancer is intriguing and usually interpreted by two distinct models." (PMID 36255267, 2022). "EXO1 expression was analyzed in 33 cancer datasets from the TCGA database." (PMID 35769911, 2022). "Such as Exonuclease 1 (EXO1) plays a role in DNA replication, DNA mismatch repair, and DNA double-strand break repair (DSBR) and has been associated with increased susceptibility to certain cancers." (PMID 35887393, 2022). "In addition, EXO1 overexpression and its relation to the resistance to chemotherapy or radiotherapy and poor prognosis was reported in multiple types of cancers 38-41." (PMID 36606188, 2022). "A deficiency in restarting the DNA replication pathway may lead to double-strand breaks, cell cycle arrest, cell death, or transformation, which may lead to cancer, and EXO1 is involved in this process." (PMID 34950206, 2021). "However, studies have shown that abnormally high expression of EXO1 is related to the occurrence, development and prognosis of various malignant tumors." (PMID 32626539, 2020). "Five genes are involved in DNA repair, a role closely related to genome maintenance and cancer, and were shown to have a protective role in various types of cancer (only one paper is cited by gene, but many others confirm this role): EXO1, ERCC1, GTF2H1, MDC1, and DGCR8." (PMID 31568528, 2019). "Clearly, the connection between EXO1 and cancer has been established and could represent a druggable target in cancers where the EXO1 protein is overexpressed." (PMID 30585186, 2018). "An increasing number of studies have highlighted the potential link between EXO1 polymorphisms and cancer risk, although no consensus has yet been obtained." (PMID 27387683, 2016). "Defects in murine Exo1 also cause only a partial loss of MMR, and similarly, mutations in human Exo1 have not been linked to the development of cancer." (PMID 26170454, 2015).
cancer (continued). "We speculate that the diverse genetic backgrounds of the cancer cell lines used in previous studies, or differential off-target effects, may account for the widely variable responses observed following EXO1 depletion by siRNA." (PMID 26160886, 2015). "Among Asian population, Exo1 K589E polymorphism was significantly associated with an increased cancer risk in all genetic models but not in the Caucasian population, this suggested that a possible ethnic difference in the genetic background." (PMID 24810280, 2014). "However, EXO1 loss is well-tolerated, suggesting the existence of compensatory mechanisms that could be exploited in DDR-deficient cancers." (PMID 41006228, 2025). "Furthermore, a total of 723 EXO1-correlated genes were identified in all cancer types." (PMID 40433389, 2025). "DNA methylation levels may play a role in the regulation of EXO1 gene expression in some cancers." (PMID 40433389, 2025). "The results revealed that EXO1 expression is positively correlated with the infiltration of T helper 2 (Th2) cells and T helper cells, and negatively correlated with natural killer (NK) CD56bright cells and plasmacytoid dendritic cells (pDC) in all six cancer types." (PMID 40433389, 2025). "Interestingly, abrogation of other components of the DDR, such as p21, Pms2 and Exo-1, can rescue survival of Terc-deficient mice without increasing cancer." (PMID 24920220, 2014). "The focused heatmap of the top 10 DEGs highlighted genes such as TPX2, MKI67, EXO1, and CTHRC1, which showed progressive upregulation from infection to cancer." (PMID 40445003, 2025). "Genes such as TPX2, MKI67, EXO1, and CTHRC1 exhibited progressive upregulation from infection to cancer, highlighting involvement in cell cycle regulation, DNA repair, and extracellular matrix remodeling." (PMID 40445003, 2025). "By employing ComBat to correct for batch effects in our study and focusing on the top DEGs, we highlighted genes such as TPX2, MKI67, EXO1, and CTHRC 1, which exhibited progressive upregulation from infection to cancer." (PMID 40445003, 2025). "Further analysis of the model genes within MOCM across pan‐cancer settings revealed that ANLN, CCNB1, CDKN3, EXO1, GJB3 and RAD51AP1 were predominantly overexpressed in tumour tissues, while GGT6 and CYP4B1 were highly expressed in normal tissues." (PMID 38958523, 2024). "Two ceRNAs (BUB1 and EXO1) from the BRCA‐COAD‐UCEC and the RRM2 from PRAD‐COAD‐UCEC were prognostic in all three cancer types included in the combination of interest." (PMID 35757968, 2022). "Alternatively, a higher EXO1 expression or activity will induce the increase of recombination rate, impaired repair of DNA double-strand breaks, telomere resection and activation of Ras/PI3K signaling pathway, which may also further increase the cancer susceptibility." (PMID 36255267, 2022). "The most frequently amplified genes across the Pan-Cancer Atlas were NBN (n = 4,275, 40.8%), EXO1 (n = 3,714, 35.4%), PARP1 (n = 3,695, 35.2%), PRKDC (n = 3,650, 34.8%) and POLB (n = 2,794, 26.6%)." (PMID 32226530, 2020). "Searching for other proliferation genes resulted in finding EXO1, MCM10, GINS2, CDT1, ORC6L, and BLM had the same pattern indicating they are most likely necessarily highly transcribed in cancer." (PMID 31857847, 2019). "The rearrangement signatures of EXO1 and FANCC knockouts were compared with cancer-derived rearrangement signatures (RS1-RS6)." (PMID 29717121, 2018). "Thus, to better understand the relationship between EXO1 and cancer, it may be necessary to analyze microsatellite-stable, but not microsatellite-unstable, cancers that display increased mutation rates." (PMID 29069084, 2017). "However, deletion of Exo1 did not appear to be a risk factor for cancer in mice lacking telomerase." (PMID 27004475, 2016).